AKAP9 (A-kinase anchoring protein 9)
Description:
Scaffolding protein that assembles several protein kinases and phosphatases on the centrosome and Golgi apparatus. Required to maintain the integrity of the Golgi apparatus. Required for microtubule nucleation at the cis-side of the Golgi apparatus. Required for association of the centrosomes with the poles of the bipolar mitotic spindle during metaphase. In complex with PDE4DIP isoform 13/MMG8/SMYLE, recruits CAMSAP2 to the Golgi apparatus and tethers non-centrosomal minus-end microtubules to the Golgi, an important step for polarized cell movement. In complex with PDE4DIP isoform 13/MMG8/SMYLE, EB1/MAPRE1 and CDK5RAP2, contributes to microtubules nucleation and extension also from the centrosome to the cell periphery. [Isoform 4]: Associated with the N-methyl-D-aspartate receptor and is specifically found in the neuromuscular junction (NMJ) as well as in neuronal synapses, suggesting a role in the organization of postsynaptic specializations.
Synonyms: AKAP-9; CG-NAP; PRKA9; AKAP350; AKAP450; KIAA0803; YOTIAO; HYPERION; MU-RMS-40.16A; PPP1R45; LQT11
Tractability: PROTAC: ubiquitination databases record sites on it; its protein half-life has been measured.
Gene: Protein-coding gene on chromosome 7 (91,940,840 to 92,110,673, forward strand). Ensembl gene ENSG00000127914.
Subcellular location: Golgi apparatus; Cytoplasm; Cytoplasm, cytoskeleton, microtubule organizing center, centrosome
Subcellular location (Human Protein Atlas): Golgi apparatus; Centrosome; Vesicles
Pathways (Reactome):
Cell Cycle: AURKA Activation by TPX2; Loss of Nlp from mitotic centrosomes; Loss of proteins required for interphase microtubule organization from the centrosome; Recruitment of NuMA to mitotic centrosomes; Recruitment of mitotic centrosome proteins and complexes; Regulation of PLK1 Activity at G2/M Transition
Muscle contraction: Phase 2 - plateau phase; Phase 3 - rapid repolarisation
Disease: Signaling by BRAF and RAF1 fusions
Organelle biogenesis and maintenance: Anchoring of the basal body to the plasma membrane
Gene Ontology:
Molecular function: molecular adaptor activity; potassium channel activator activity; potassium channel regulator activity; protein binding; protein kinase A regulatory subunit binding; transmembrane transporter binding; signaling receptor binding; DNA binding
Biological process: cellular response to cAMP; maintenance of centrosome location; microtubule nucleation; positive regulation of microtubule polymerization; protein-containing complex localization; regulation of cardiac muscle cell action potential involved in regulation of contraction; regulation of Golgi organization; regulation of heart rate by cardiac conduction; regulation of membrane repolarization; regulation of ventricular cardiac muscle cell membrane repolarization; chemical synaptic transmission; signal transduction
Cellular component: centrosome; cis-Golgi network; cytoplasm; glutamatergic synapse; Golgi apparatus; Golgi stack; potassium channel complex; voltage-gated potassium channel complex; cytoskeleton; cytosol; synaptic membrane; microtubule organizing center
Genetic constraint (gnomAD): Loss-of-function variants: 251 observed, 420.98 expected, observed/expected ratio (o/e) 0.6, 90% interval 0.54 to 0.66. The upper end of that interval is the gene's LOEUF score, 0.66, which puts it in group 2 of 6, group 1 being the genes least tolerant of losing a copy. Missense variants: 3,814 observed, 4,177.3 expected, observed/expected ratio (o/e) 0.91, 90% interval 0.89 to 0.94. Synonymous variants: 1,354 observed, 1,438.2 expected, observed/expected ratio (o/e) 0.94, 90% interval 0.9 to 0.99.
Gene-disease validity (ClinGen):
ClinGen rates the evidence that AKAP9 causes each of these diseases.
long QT syndrome (autosomal dominant): Disputed.
Homologues: Orthologues: chimpanzee AKAP9 (99% identical), chimpanzee AKAP9 (98% identical), macaque AKAP9 (96% identical), dog AKAP9 (87% identical), pig AKAP9 (86% identical), rabbit AKAP9 (84% identical), guinea pig AKAP9 (82% identical), rat Akap9 (70% identical), mouse Akap9 (69% identical), tropical clawed frog akap9 (47% identical). Paralogues in human: PCNT (19% identical).
Diseases named in the same sentence as AKAP9 in open-access papers:
AKAP9 is named in the same sentence as 67 diseases in open-access papers, as found by Europe PMC text mining. Sharing a sentence is not in itself a finding about the gene and the disease. The quoted sentences say what the papers report.
breast carcinoma (12 papers, 2014 to 2022). "A-kinase anchoring protein (AKAP) 9 was also affected by sEH deletion but, while some AKAP proteins have been linked with angiogenesis, AKAP9 has stronger links with breast cancer cell migration." (PMID 34281173, 2021). "AKAP9 (encodes A-kinase anchor proteins-9) is involved in the development of metastasis of several cancers, including colorectal cancer, breast cancer, lung cancer, melanomas, thyroid carcinomas." (PMID 31426369, 2019). "The non-synonymous SNP M463I (rs6964587) in AKAP9 was also found to be very an important breast cancer susceptibility polymorphism." (PMID 29370121, 2018). "The single nucleotide polymorphisms M463I, 1389G > T and N2792S, 8375A > G in AKAP9 were found to increase the risk of familial breast cancer in German women." (PMID 29370121, 2018). "In summary, in this very large case–control study focused on common candidate non-synonymous variants, we have identified a novel susceptibility locus at 3p21 and confirmed AKAP9-rs6964587 as a marker of a breast cancer risk at 7q21." (PMID 24943594, 2014). "Additionally, specific polymorphisms in AKAP9 are associated with increased risk in familial breast cancers." (PMID 29433456, 2018). "An analysis of the Cancer Genome Atlas (TCGA) dataset shows that EPAC1, PKA, A-kinase anchoring protein 9 (AKAP9), and other cAMP signaling components are amplified in breast cancer patients, and this is linked to a lower chance of survival." (PMID 35805104, 2022). "Yotiao, which is also known as AKAP9, is involved in the development and metastasis of several cancers, including breast cancer, lung cancer, melanomas, thyroid carcinomas, and colorectal cancer." (PMID 32028718, 2020). "Interestingly, AKAP5, AKAP9, AKAP11 and AKAP12 is expressed at lower levels in the basal-like and, less prominently in HER2-enriched subtypes, the breast cancer subtypes with highest risk of recurrence." (PMID 29433456, 2018). "Variants in AKAP9 have been described repeatedly in COSMIC and as SNPs associated with increased breast cancer risk, but the particular variant found here has not yet been reported." (PMID 27270325, 2016). "A number of these AKAPs have been reported to correlate with the occurrence of different cancer subtypes, including AKAP3 (ovarian cancer), AKAP4 (multiple myeloma), AKAP9 (breast cancer), AKAP10 (breast cancer) and AKAP13 (colorectal cancer and breast cancer)." (PMID 26272591, 2015).
long QT syndrome (12 papers, 2014 to 2026). "The variant NM_005751.5(AKAP9):c.3708A>T, in sample 5, was observed in the literature in Long QT Syndrome and Romano-Ward Syndrome, two inherited cardiac diseases that can be correlated with sudden death." (PMID 41300725, 2025). "Rare variants in AKAP9 are associated with AD and cardiac abnormalities, including long QT syndrome." (PMID 41561974, 2025). "The genetic test indicated a heterozygous mutation, namely, c.11714T > C (p.M3905T), in the AKAP9 gene, which is a controversial gene in long QT syndrome." (PMID 36699290, 2023). "Akap9 interacts with members in signaling transduction pathways (e.g., protein kinase A, serine/threonine kinase protein kinase N, protein phosphatase 1) and loss-of-function mutations are associated with Long QT syndromes." (PMID 30782122, 2019). "AKAP9 was associated with a single case of long QT syndrome and might rather be a QT interval modifier than a long QT causal gene." (PMID 28315637, 2017). "AKAP9 mutations cause long-QT syndrome manifested by cardiac arrhythmia." (PMID 25961040, 2015). "Therefore, the AKAP9 variant is associated with long QT syndrome (LQTS)." (PMID 41574642, 2026). "In skeletal muscle AKAP9 is predominantly localized subjacent to acetylcholine receptors in the neuromuscular junction and was seen within the Z-line, and in cardiac muscle it has been recently identified as a gene associated with long-QT syndrome (LQTS), manifested by cardiac arrhythmia." (PMID 25961040, 2015). "PVs and LPVs in the ABCC9, AKAP9, ANK2, and SCN10A have been implicated in conduction defects and arrhythmias, particularly the long QT syndromes and conduction defects." (PMID 34790974, 2021). "In the case of KCNQ1, loss of interaction between AKAP9 and KCNQ1 leads to a potentially fatal heart condition, long-QT syndrome, which also arises in cases with loss of function mutations in KCNQ1 itself." (PMID 24467814, 2014). "SNP in AKAP9 Gln3531Glu was found to be one the novel rare AKAP variants that was observed in congenital arrhythmia cases, which was also highly common in drug-induced Long-QT syndrome (LQTS)." (PMID 29370121, 2018). "Among the genes associated with long QT syndrome, only AKAP9 and CALM2 are not included in the clinical exome of Illumina." (PMID 28315637, 2017).
colorectal cancer (9 papers, 2016 to 2024). A primary or metastatic malignant neoplasm that affects the colon or rectum. "Mutation of AKAP9 is closely related to the high microsatellite instability of gastric and colorectal cancers." (PMID 39317949, 2024). "High expression of AKAP9 is also associated with low survival in patients with colorectal cancer (CRC)." (PMID 34679534, 2021). "TRIP10, also known as CIP4, is controlled by AKAP9 and aids in the development of colorectal cancer." (PMID 37168510, 2023). "Promotes cellular proliferation, migration, and invasion via 1) binding to SFPQ and releasing oncogene PTBP2 from SFPQ/PTBP2 complex 2) increasing expression of AKAP-9 via promoting SRPK1-catalyzed SRSF1 phosphorylation in colorectal cancer cells." (PMID 27888635, 2017). "In addition, MALAT1 may also promote colorectal cancer development by directly targeting AKAP9." (PMID 27458156, 2016). "Our earlier findings indicate that the long non-coding RNA MALAT1 promotes colorectal cancer (CRC) cell proliferation, invasion and metastasis in vitro and in vivo by increasing expression of AKAP-9." (PMID 26887056, 2016).
Alzheimer disease (7 papers, 2018 to 2022). A progressive, neurodegenerative disease characterized by loss of function and death of nerve cells in several areas of the brain leading to loss of cognitive function such as memory and language. "The AKAP9 genetic variant was initially identified by whole exome sequencing in an African-American discovery cohort of Alzheimer’s disease cases and controls." (PMID 34864818, 2021). "As part of these efforts, we also utilized XMAS-TREE to enrich for cells that have been edited at several disease-relevant loci including those associated with sickle-cell anemia (i.e., HBG1, HBG2) and Alzheimer’s disease (i.e., AKAP9, PSEN1)." (PMID 33317513, 2020). "We previously identified by whole exome sequencing two rare specific variants in AKAP9 (rs144662445 and rs149979685) in a sample of African American (AA) Alzheimer disease (AD) cases and controls." (PMID 29516269, 2018). "Moreover, two AKAP9 mutations (rs144662445 and rs149979685) were associated with Alzheimer disease by increasing Tau phosphorylation." (PMID 36317124, 2022). "For example, we found Alzheimer’s Disease risk genes APOE, PLD3, TREM2, UNC5C, AKAP9, and ADAM10 in our orthologous gene list." (PMID 30382841, 2018). "In this regard, we co-transfected hPSCs with pEF-XMAS1xStop/2xStop and pEF-ABEmax along with a pDT-sgRNA targeting genomic Site-1 or single base pair changes in AKAP9 and PSEN1 that have been previously associated with increased risks of developing Alzheimer’s disease (AD)." (PMID 33317513, 2020).
cardiomyopathies (6 papers, 2017 to 2024). "In particular, the KCNE1, MYBPC3, and AKAP9 genes that were associated with LQTS or cardiomyopathy would have been suspicious as genes associated with cause of death because of an AD mode of inheritance." (PMID 34728707, 2021). "The majority of the VUS has been identified in genes previously having been reported to be associated with cardiac channelopathies (SCN5A, AKAP9, RYR2) and cardiomyopathies (RBM20, RAF1, DSG2)." (PMID 33789662, 2021). "AKAP9 variants were associated with types of cardiovascular including LQTS type 11, Brugada syndrome, sudden death of unknown cause, severe ventricular arrhythmias, and cardiomyopathy." (PMID 39272661, 2024). "Furthermore, variants in AKAP9 and DLG1 genes could act as genetic modifiers of arrhythmic risk and phenotype severity in cardiomyopathies." (PMID 28750076, 2017).
thyroid cancer (6 papers, 2013 to 2024). "So far, the only known association of the AKAP9 gene with thyroid cancer was the effect of chromatin rearrangement and the formation of an AKAP9-BRAF fusion protein with elevated kinase activity." (PMID 38203733, 2024). "In thyroid carcinoma, increased expression of AKAP9 is correlated with more advanced tumours (expressed by the pT scale and the AJCC scale) and older age of patients." (PMID 38203733, 2024). "Other types of BRAF mutations are rarely described in thyroid cancer: the BRAF V599ins, BRAF V600E+K601del, BRAF K601E, AKAP9-BRAF, and V600D+FGLAT601- 605ins, which result from an insertion of 18 nucleotides at nucleotide T1799." (PMID 24868250, 2013). "AKAP9 expression increase over 0.94 may indicate FTC, so it can be treated as a hallmark of a more aggressive thyroid cancer." (PMID 38203733, 2024). "AKAP9 involvement in cancer disease was first mentioned in thyroid cancers, where chromatin rearrangement (paracentric inversion of chromosome 7q) results in the formation of an AKAP9-BRAF fusion protein that affects B-Raf action and constitutively activates the MAPK pathway." (PMID 38203733, 2024). "Here, we have analysed for the first time whether the AKAP9 gene expression is related to the development or progression of thyroid cancer, as observed in CRC, gastric cancer, or leukaemia." (PMID 38203733, 2024). "Interestingly, it has been demonstrated that BRAF-AKAP9 gene fusion leads to activate the MAPK pathway in human thyroid cancer, and AKAP9 is crucial for sertoli cell maturation and spermatogenesis in mice." (PMID 28553232, 2017). "AKAP9 regulates activation-induced retention of T lymphocytes at sites of inflammation and is related to the activation of the MAPK pathway in thyroid cancer." (PMID 33468065, 2021). "In thyroid cancers, the mechanism of increased expression of AKAP9 and its influence on tumour development has not yet been elucidated." (PMID 38203733, 2024).
Tinnitus (5 papers, 2022 to 2025). Tinnitus is an auditory perception that can be described as the experience of sound, in the ear or in the head, in the absence of external acoustic stimulation. "A whole exome sequencing study of severe tinnitus reported an enrichment of rare missense variants in several synaptic genes, including ANK2, AKAP9 and TSC2, in a Spanish cohort of Meniere’s Disease (MD) patients with catastrophic tinnitus (N=59)." (PMID 41378354, 2025). "In Spanish patients with MD, using exome sequencing and gene burden analyses, severe tinnitus has been associated with rare missense variants in 24 synaptic genes, including ANK2, TSC2, and AKAP9." (PMID 38254912, 2023). "We also found some rare variants previously reported in genes associated with tinnitus such as ANK2, AKAP9 and TSC2." (PMID 36450758, 2022). "Individuals with missense variants in known genes described for severe tinnitus such as ANK2, TSC2, and AKAP9 were targeted for specific LSVs overlapping these genes." (PMID 36450758, 2022). "Previous research revealed the presence of genes related with axonal branching (ANK2, AKAP9, and TSC2) in tinnitus patients." (PMID 38562529, 2024). "Moreover, gene burden analyses in sequencing data from Spanish and Swede patients with severe tinnitus have identified and replicated ANK2, AKAP9, and TSC2 genes." (PMID 38334885, 2024). "Although several rare missense SNVs were reported in MD and severe tinnitus, including ANK2, TSC2, and AKAP9 genes, these variants do not explain the presence of other comorbidities with a higher prevalence." (PMID 38254912, 2023).
channelopathies (4 papers, 2019 to 2025). "Of interest, some patients may carry the AKAP9 variant and other genes associated with channelopathies, suggesting the complexity of multifactorial and polygenic inheritance in these patients." (PMID 39272661, 2024). "One of the cases analyzed (ADN001) was previously reported by our group in a study of channelopathies, which described the coexistence of mutations in KCNH2, AKAP9, and the TTN p.Arg34653Cys variant, now reevaluated in this study." (PMID 41465321, 2025).